SDHB (succinate dehydrogenase complex iron sulfur subunit B)
Diseases named in the same sentence as SDHB in open-access papers (continued):
Sharing a sentence is not in itself a finding about the gene and the disease.
paraganglioma (continued). "Additionally, for the genes associated with this pathway we found evidences of similarity with SDHB-mutant pheochromocytoma/paraganglioma." (PMID 33806389, 2021). "This aggregate result underscores the different tumor spectrum of SDHA-germline variant carriers and Carney Stratakis Syndrome patients, which are known to harbor SDHB, SDHC, or SDHD mutations, and to develop invariably the association of GIST and paraganglioma during their life course." (PMID 35059314, 2021). "They identified the pathways that distinguishes SDHB-metastatic from all other types of pheochromocytoma/paraganglioma and suggest that activation of the EMT process might be associated to the particularly invasive phenotype of this group of tumors." (PMID 33806389, 2021). "In 6 of them, we revealed the existence of pathogenic/likely pathogenic variants of genes encoding for components of the SDH complex (SDHB, SDHD, SDHAF3, and SDHAF4), confirming their high mutation frequency not only in paragangliomas and pheochromocytomas but also in VPGLs as distinct tumor types." (PMID 32948195, 2020). "Screening for SDHB and SDHD mutations may be also be prudent in patients with paragangliomas in certain uncommon locations such as the mediastinum or the organ of Zuckerkandl." (PMID 30456751, 2018). "In addition, per the most recent Endocrine Society Clinical Practice Guideline published in 2014, patients with paragangliomas should undergo genetic testing for SDH mutations, and those with metastatic disease should undergo evaluation for SDHB mutations." (PMID 30456751, 2018). "To further clarify the role of loss of the maternal copy of 11p in relation to loss of the long arm of chromosome 11 in paragangliomas, we used several genetic approaches to determine the allelic status of chromosome 11 in SDHAF2, SDHD, SDHB, and VHL mutant PGLs/PCCs." (PMID 28099933, 2017). "Notably, oncogenesis under the conditions of FH deficiency follows a genetic pathway similar to that in malignant SDHB-mutant paragangliomas/pheochromocytomas." (PMID 28187001, 2017). "If the phaeochromocytoma or the paraganglioma is due to an SDHB mutation, staining the tumour for SDHB will be negative with a sensitivity of 100% and specificity of 84% for any type of SDH mutation." (PMID 29166454, 2017). "We describe the first patient with an SDHB mutation who developed a paraganglioma and a clinically non-functioning gonadotroph carcinoma." (PMID 28284009, 2017). "SDHAF2 mutations may present similarly to mutations in SDHA, SDHB, SDHC and SDHD as paraganglioma and pheochromocytoma." (PMID 26839416, 2016). "Patients with germline mutations in SDHB may develop both GIST and paraganglioma (= Carney-Stratakis syndrome)." (PMID 25886494, 2015). "Paragangliomas may occur sporadically or in hereditary syndromes associated or caused by VHL and SDHB mutations." (PMID 22344361, 2012). "Mutations in SDH subunits B (SDHB), C (SDHC), and D (SDHD), in particular, have been associated with familial cancer predisposition syndromes with affected individuals at increased risk for the development of paragangliomas and pheochromocytomas." (PMID 23036227, 2012). "Strikingly, inactivating germline mutations in SDHB or SDHC genes have been also identified in sporadic WT GISTs occurring in patients without a personal or family history of paraganglioma." (PMID 22974104, 2012). "Here we describe the results of SDHB gene deletion scanning of 126 paraganglioma-PCC patients." (PMID 19368708, 2009). "Interestingly, Carney-Stratakis syndrome, characterized by germline mutations in SDHB, SDHC, or SDHD, is a hereditary syndrome associated with GIST and paraganglioma, and may also be associated with SDH-mutant RCC." (PMID 40018405, 2025).
paraganglioma (continued). "Carney-Stratakis syndrome (CSS), a rare condition characterized by paragangliomas and/or pheochromocytomas and gastrointestinal stromal tumors (GIST), is caused by germline heterozygous pathogenic variants in the succinate dehydrogenase subunit genes (SDHB, SDHC, SDHD)." (PMID 40242210, 2025). "Some hereditary paragangliomas, particularly head and neck PGLs (HNPGLs), are predominantly associated with the pseudohypoxia cluster and germline succinate dehydrogenase subunit SDHD and SDHB variants, indicating the need for genetic counseling and testing for all patients with PGLs." (PMID 40917352, 2025). "One SDHD and one SDHB germline variant of uncertain significance were identified in five patients affected by sporadic cases of Cushing’s disease, who did not have any history or sign of pheochromocytoma or paraganglioma." (PMID 35743266, 2022). "In addition to their role in primary mitochondrial disease, heterozygous germline variants in other complex II subunits and assembly factors (including SDHA, SDHB, SDHC, SDHD and SDHAF2) are associated with paragangliomas, phaeochromocytomas and gastrointestinal stromal tumours." (PMID 34012134, 2021). "Furthermore, Chromogranin A does not provide an additive benefit to standard surveillance for predicting the presence of SDHB- or SDHD-related paraganglioma but has a useful negative predictive value when normal in patients with an SDHB mutation." (PMID 34072806, 2021). "Thus far, no curative therapies are available for malignant SDHB-associated phaeochromocytomas and paragangliomas (PPGLs)." (PMID 34680273, 2021). "The lifetime risk of RCC in SDHB mutation carriers is not well defined, but likely less than 10–15%; however, annual or biannual renal surveillance by MRI can be combined with screening for phaeochromocytoma/paraganglioma (which commences in older children)." (PMID 29680948, 2018). "Furthermore, SDHB or SDHD mutations were detected in the majority of patients with organ of Zuckerkandl paragangliomas, another rare site of paraganglioma occurrence located around the origin of the inferior mesenteric artery and extending to the level of the aortic bifurcation." (PMID 30456751, 2018). "Furthermore, among the conditions related to mutations in the SDHx genes, the Carney diad (or Carney-Stratakis diad) syndrome is associated with mutations in the SDHB, SDHC, and SDHD genes and manifests as paragangliomas and gastrointestinal stromal tumors in patients of either sex." (PMID 28187001, 2017). "The development of these molecules (PT2385 and PT2399) have may provide a therapeutic opportunity to perhaps successfully treat pharmacologically several types of cancers which currently have limited therapeutic options (e.g. patients with SDHB-related metastatic phaeochromocytoma/paraganglioma)." (PMID 29166454, 2017). "Nenhuma alteração genética dos genes VHL e SDHB foi detectada nos tecidos tumorais e adjacentes ao tumor, o que nos levou a afastar uma síndrome hereditária que poderia explicar a associação entre o paraganglioma e o CCRC em um paciente com hipertensão arterial." (PMID 22344361, 2012). "Notably, this case identified rare co-occurring variants, an SDHB pathogenic variant and a KIF1B VUS, underscoring the critical need for comprehensive germline and somatic genetic testing in such cases, offering valuable insights and data for the diagnosis, management, and research of paraganglioma." (PMID 40917352, 2025). "Here we report the analysis of the SDHB and SDHC genes in this group of patients and in addition the analysis of 5 families presenting with pheochromocytoma and/or paraganglioma." (PMID 16405730, 2006). "It is now recognised that SDHD and SDHB, together with the VHL, RET and NF1 genes, play a major role in the hereditary forms of both pheochromocytoma and paraganglioma." (PMID 16288654, 2005).
paraganglioma (continued). "In addition to moderate to strong SDHB staining, we observed an absence of immunostaining for 5hmC in all 3 tumors, indicating a hypermethylated tumor profile, which is characteristic of tumors associated with SDHx defects and paragangliomas in patients harboring pathogenic variants in SLC25A11." (PMID 40242210, 2025). "In this study, we investigated a woman who presented with pheochromocytoma, paraganglioma, and GIST, fulfilling the criteria for CSS but lacking pathogenic variants or gene deletions in the SDHB, SDHD, or SDHC genes." (PMID 40242210, 2025). "The syndromic presentation of HNPGLs is associated with mutations in SDHD (paraganglioma syndrome type 1, PGL1), SDHAF2 (PGL2), SDHC (PGL3), SDHB (PGL4), SDHA (PGL5), VHL (von Hippel–Lindau syndrome), HIF-2α (paraganglioma–somatostatinoma–polycythemia), and NF1 (neurofibromatosis type 1 syndrome)." (PMID 39684472, 2024). "Indeed, it was shown that mutations in SDHA account for around 30% of all KIT/PDGFRA-WT GIST, while being responsible for <1% of all pheochromocytoma and paraganglioma cases (PPGL), as opposed for example to SDHB that accounts for about 10% of all PPGL." (PMID 35059314, 2021). "SDHB-negative paragangliomas are reported to be of higher malignancy, which is mirrored also in our investigation by the significantly higher Ki-67 values of SDHB-negative tumors." (PMID 29163802, 2017). "The scarcity of SDHAF2 mutations was reinforced by the failure to document mutations in this gene among 315 patients with paraganglioma and without mutations in the SDHD, SDHC, or SDHB genes." (PMID 24899893, 2014). "Since the SDHB group did not develop paraganglioma during a median follow-up time of 5.92 years, the screening interval could be longer." (PMID 39881751, 2025). "Taking these differences into account, we still noted that several genes were missing in the PanelApp panels which most likely would fulfill their criteria, for instance the leukemia predisposing genes ETV6 and RUNX1 (not mentioned) and the hereditary paraganglioma gene SDHB (marked red)." (PMID 34061292, 2021). "In view of the contradictory results in literature, in the present study the SST expression pattern was re-evaluated in a large set of paragangliomas, differentiating between parasympathetic and sympathetic tumors, primary tumors and metastases, and SDHB positive and negative cases." (PMID 29163802, 2017). "Additionally, all 3 tumors (pheochromocytoma, paraganglioma, and GIST) in our case exhibited a hypermethylation status similar to that of SDH-mutated tumors, characterized by a lack of 5-hmC immunostaining and retained SDHB protein expression." (PMID 40242210, 2025). "In a study of 34 patients with sporadic WT GISTs without a family history of paraganglioma, 12% of patients were found to have germline mutations in SDHB or SDHC, while those who did not harbor a detectable SDH mutation demonstrated significantly decreased SDHB protein expression." (PMID 30456751, 2018). "Specificity, sensitivity, positive and negative predictive value of apelin, SDHB and CHGB in differentiating metastatic from non-metastatic pheochromocytoma and paraganglioma." (PMID 35574028, 2022). "In fact, no paragangliomas occurred at all during the follow-up of the SDHA and SDHB group." (PMID 39881751, 2025).
pheochromocytoma (182 papers, 2004 to 2026). "SDHB-mutant (metastatic) pheochromocytomas exhibit a high risk of malignancy, and succinate accumulation drives epigenetic dysregulation." (PMID 40649858, 2025). "Pathogenic variants of SDHB, as in our patient, lead to pheochromocytoma/paraganglioma syndrome type 4 (PGL4)." (PMID 39896955, 2025). "included one mother with a likely pathogenic variant in PKD2, causative of polycystic kidney disease type 2, and another mother with a likely pathogenic variant in SDHB, causative of pheochromocytoma." (PMID 39960876, 2025). "This retrospective study proposed a convenient and informative tool for predicting SDHB mutations in pheochromocytoma and retroperitoneal PGLs by integrating easily obtained clinical, biochemical, and functional imaging characteristics." (PMID 38179299, 2023). "Given the high degree of suspicion for PCC, an open laparoscopic adrenalectomy was performed with histology confirming SDHB gene mutation positive giant pheochromocytoma." (PMID 36742443, 2023). "Succinate dehydrogenase subunit B (SDHB) and fumarate hydratase (FH) staining were retained; however, weakly positive 2SC staining raised concerns for FH-deficient pheochromocytoma." (PMID 37908587, 2023). "The use of temozolomide should be highly considered in patients with SDHB variants who develop metastatic paragangliomas and pheochromocytomas." (PMID 35685436, 2022). "Used in the management of metastatic paragangliomas and pheochromocytomas, evidence has shown patients with SDHB variants respond remarkably well to temozolomide-based regimens." (PMID 35685436, 2022). "In pheochromocytoma cells with low expression of SDHB, pseudohypoxia is associated with iron accumulation, which contributes to elevated oxidative stress in these cells." (PMID 35159368, 2022). "Elevation of plasma methoxytyramine levels, solitary or together with other plasma metanephrines, has been found in up to 70% of patients with pheochromocytomas arising in the setting of SDHB and SDHD variants." (PMID 35205664, 2022). "The RS0 xenograft is the most successful cell model of SDHB-deficient pheochromocytoma, which has the potential to study the HIF system in detail in a mammal." (PMID 34957538, 2021). "Our findings are in line with increased ROS levels in the mitochondria of SDHB-deficient mouse phaeochromocytoma cells, confirmed by two SDHB-silenced cell lines and one SDHC-mutated transgenic mouse cell line." (PMID 34680273, 2021). "Lactate produced by cancer-associated fibroblasts was also taken up by pheochromocytoma spheroids when a 3D-co-culture was performed and SDHB was silenced." (PMID 34957538, 2021). "Recently, SDHB-deficient pheochromocytoma has been cultivated in xenografts and has generated cell lines, which can be traced back to a heterozygous SDHB-deficient rat." (PMID 34957538, 2021). "In certain tumor entities such as pheochromocytomas genetic predisposition together with SDHB mutations have been described to lead to functional loss of SDHB." (PMID 31877753, 2019). "In face of the malignant presentation, molecular studies were conducted to screen mutations in five genes related to pheochromocytoma: SDHB, SDHD, SDHC, MAX and VHL." (PMID 29768630, 2018). "In patients with SDHB‐linked HNPGLs, these regions should be evaluated not only for the occurrence of concurrent PGLs and phaeochromocytomas, but also for SDHB‐associated non‐paraganglionic tumours and PGL metastases." (PMID 29951630, 2018). "A 41-yr-old female participant was found to have a likely pathogenic frameshift variant in SDHB, a gene in which variants cause autosomal dominant hereditary paraganglioma and pheochromocytoma." (PMID 30487145, 2018).
pheochromocytoma (continued). "The presence of malignant features can suggest certain genetic defects; phaeochromocytomas and especially extra-adrenal paragangliomas of malignant nature are associated mostly with SDHB mutations (in 30% patients)." (PMID 29166454, 2017). "Subsequent genetic testing identified a likely pathogenic variant in SDHB, confirming a diagnosis of Hereditary Paraganglioma-Pheochromocytoma syndrome." (PMID 26236513, 2015). "Since mutations in SDHB gene are the most frequent cause of metastatic paraganglioma tumors, it has consistently been proposed that all patients presenting with malignant paraganglioma/pheochromocytoma should be tested for SDHB gene mutations." (PMID 24899893, 2014). "Genetic syndromes of pheochromocytoma include multiple endocrine neoplasia type 2 (MEN2A and 2B), neurofibromatosis type 1 (NF1), the pheochromocytoma-paraganglioma syndrome (mutation of the SDHB or SDHD genes), and von Hippel-Lindau syndrome (VHL)." (PMID 23401807, 2013). "Mitochondrial complex II is a component of the electron transport chain, and mutations of SDHB or SDHD genes that abrogate the oxidoreductase function of complex II can cause pheochromocytomas." (PMID 16103922, 2005). "Germline mutations in the succinate dehydrogenase (SDH) (mitochondrial respiratory chain complex II) subunit B gene, SDHB, cause susceptibility to head and neck paraganglioma and phaeochromocytoma." (PMID 15505628, 2004). "SDHB maps to 1p36, a region of frequent allele loss in many tumour types including neuroblastoma and phaeochromocytoma." (PMID 15505628, 2004). "Patient #52, with a unilateral cataract, had Hereditary Paraganglioma-Pheochromocytoma Syndrome; he tested positive for the same SDHB variant as his affected father (who had the same syndrome and childhood cataracts), but this gene has not been directly implicated in congenital cataracts." (PMID 36980880, 2023). "However, SDHB gene mutations and urinary metanephrine secretion are important risk factors associated with the presence of pheochromocytoma as well as with malignant development." (PMID 35582561, 2022). "Interestingly, metformin treatment of pheochromocytoma/CAFs co-cultures reduced CAF-induced-migration and invasiveness of succinate dehydrogenase subunit B (SDHB)-deficient pheochromocytoma cells grown as spheroids." (PMID 36582801, 2022). "Similarly, the role of TKIs in the treatment of advanced/metastatic paraganglioma and pheochromocytoma is encouraging, with evidence of a patient harboring an SDHB variant responding to sunitinib-based therapy." (PMID 35685436, 2022). "Only a single patient in this SDHB‐linked HNPGL cohort developed a phaeochromocytoma." (PMID 29951630, 2018). "Germline SDHB mutations account for an estimated 22–38% of hereditary pheochromocytomas/PGLs." (PMID 27896548, 2017). "Moreover, hereditary paraganglioma and pheochromocytoma is the main disease state for SDH deficiency which occurs due to mutation of SDHB, SDHC or SDHD subunits." (PMID 27051561, 2016). "Suppressed SDHB protein can be found in pheochromocytomas with loss of VHL." (PMID 20398431, 2010). "This potential mechanism might apply especially to SDHB because its mutations are associated with malignancy and early-onset pheochromocytomas that could lead to severe hypertensive crises." (PMID 17376234, 2007). "In addition, malignant pheochromocytoma children with a high Pheochromocytoma of the Adrenal Gland Scaled Score and succinate dehydrogenase complex iron sulfur subunit B mutation require a long-term follow-up or even unplanned surgery because of the higher risk of recurrence." (PMID 38439039, 2024). "In addition, patients and their physicians may have been unaware that phaeochromocytomas and some non‐paraganglionic tumours such as GISTs, pituitary tumours and renal clear cell carcinomas are part of the tumour spectrum caused by SDHB germline mutations." (PMID 29951630, 2018).